CD86 (CD86 molecule)
Diseases named in the same sentence as CD86 in open-access papers (continued):
Sharing a sentence is not in itself a finding about the gene and the disease.
atherosclerosis (continued). "The role of CD80 and CD86 expression on B cells in atherosclerosis is less clear." (PMID 33572939, 2021). "In this study, we suggested that the progression of atherosclerosis might be related to CD86, C1QB, CD53, C1QC, NCF2, and ITGAM and that it plays a role in regulating immune-competent cells such as T cell CD8 and macrophages M0 and M2." (PMID 32821283, 2020). "CD80 and CD86 expressed by activated APCs are promising imaging targets in atherosclerosis." (PMID 26728358, 2016). "According to the previous studies, the data have shown that the CD28/CTLA-4-CD80/CD86 pathway plays an important role in accelerating the development of atherosclerotic lesions, and was considered as an important potential target in immune regulation of atherosclerosis." (PMID 35874761, 2022). "We also identify key regulatory axes, such as CD47/Sirpa and Selplg/Vsir in AAA, and CD48/CD2, CD86/CD80, and CTLA-4/PD-1 in atherosclerosis, as potential therapeutic targets." (PMID 41216502, 2026). "Consistent with our data-mining analysis, CD155 and CD274 expression levels were significantly reduced in ApoE−/− aortas, while CD86 levels were increased, supporting the immunosuppressive roles of CD155 and CD274 during atherosclerosis." (PMID 41216502, 2026). "T cell costimulatory signals such as the CD28–CD80/CD86 and CD27–CD70 pathways protect against atherosclerosis by systemically shifting the Th1 cell/Treg balance toward Treg responses." (PMID 40608058, 2025). "It has been reported that macrophage polarization plays a key role in the progression of atherosclerosis, so we tested the expression of marker proteins (CD14, CD86, and CD206) by Western blot." (PMID 36159969, 2022). "What’s more, APC-like neutrophils foster T cell response via HLA-DR, CD80 and CD86 in vitro, implying an immunostimulatory effect of APC-like neutrophils in atherosclerosis." (PMID 35251050, 2022). "Our recent study demonstrated that overexpression of CTLA-4 in T cells inhibited atherosclerosis development in Apoe−/− mice by downregulating the CD80 and CD86 expression on DCs and limiting the CD80/CD86–CD28-dependent activation of Teffs." (PMID 34945203, 2021). "As shown, CD86 and macrophage M2 (R = 0.57, p = 0.041) and C1QB and T cell CD8 (R = −0.63, p = 0.02) represented good correlation in early atherosclerosis plaque samples." (PMID 32821283, 2020). "Among the hub genes, TNF, PTPRC (also known as CD45), VCAM1, CD86 and MMP9 have been confirmed as inflammatory biomarkers of atherosclerosis." (PMID 32213192, 2020). "Moreover, the suppression of CD86, an antigen presentation marker linked to T-cell priming and chronic inflammation, suggests that EVOOPE+ may dampen the interface between innate and adaptive immunity, a relevant target in atherosclerosis and metabolic syndrome." (PMID 41303649, 2025). "CD86 expression is markedly elevated in intermediate and non-classical monocytes, which are highly pro-inflammatory and contribute to the development of atherosclerosis." (PMID 40805981, 2025). "Similarly, in atherosclerosis, enhanced M1 marker expression (e.g., CD40/CD86) strengthens adaptive immunity." (PMID 41011253, 2025). "These six hub genes, TYROBP, ITGAM, ITGB2, CD86, PLEK, LCP2 may be important biomarkers for the progression of atherosclerosis and potential treatment targets." (PMID 38382092, 2024). "Macrophages express CD80, CD86 and CD28 in human atherosclerosis lesions." (PMID 36703734, 2022). "Atherosclerosis was ameliorated and the production of IFN-c in the lymph nodes and spleen was reduced by their effector T cells in both CD80 and CD86-deficient hyperlipidemic animals." (PMID 36703734, 2022). "CTLA-4-Ig that binds to CD80 and CD86 and has an inhibitory effect on the CD80/CD86–CD28 costimulation pathway is clinically effective in treating rheumatoid arthritis, and has also been shown to protect against experimental atherosclerosis." (PMID 34945203, 2021).
atherosclerosis (continued). "CD86, a biomarker of M1-type macrophages, is markedly expressed in vulnerable arterial plaques.M1-type macrophages release ROS and pro-inflammatory cytokines, such as TNF-α, IL-1β, IL-6, and IL-12, which damage endothelial cells and blood vessels and promote atherosclerosis." (PMID 38382092, 2024). "Since activated APCs that express CD80 and CD86 are a primary component of atherosclerotic lesions and the amount of APCs correlates with plaque vulnerability, CD80 and CD86 may be promising imaging targets in atherosclerosis." (PMID 26728358, 2016).
viral infection (38 papers, 2009 to 2026). "CD86 gene expression is induced in dendritic cells and Langerhans cells by interferon gamma as well as bacterial and viral infections." (PMID 39302712, 2024). "Given the fundamental functions of activated microglia during viral infection of the brain, we aimed to assess the expression of microglial activation markers CD86 and CD80 on microglia infected with either MP-12 or ZH501." (PMID 38392897, 2024). "To evaluate how viral infection modulates the activation status of unswitched memory B cells, we evaluated the expression of the CD86 and CD69 activation antigens as well as the CD21 co-receptor on total memory B cells (rather than antigen-specific B cells)." (PMID 37638016, 2023). "The B7 family proteins B7.1 (CD80) and B7.2 (CD86) are two well-studied costimulatory ligands that play critical roles in host T cell immunity against viral infection." (PMID 37626059, 2023). "Virus infection promoted the upregulation of CD1d and CD86 on monocytes, and the CD1dhighCD86high monocytes were easier to be targeted and eliminated by AlloHSC-iNKT cells, resulting in a residual CD1dlowCD86low population." (PMID 35313965, 2022). "The surface cell stimulator ligands CD80 and CD86 play a vital part in the maintenance and initiation of the immune response against viral infections." (PMID 28265274, 2017). "When MoDCs were treated with 5 × 106 CFU heat killed pneumococci at 6 hr after virus infection, the expression of CD86 was significantly higher than that infected with influenza virus alone." (PMID 21771345, 2011). "During viral encephalitis, the major group of MHC class II proteins, as well as the costimulatory molecules CD40, CD16, CD32, and CD86, are expressed on the surface of activated M1 microglia following viral infection, while M2 microglia typically express CD206 and ARG-1." (PMID 36918933, 2023). "It was reported that primary viral infection might cause an IFN-I-dependent and systemic “partial” activation of T lymphocytes that was characterized by up-regulated expression of early activation marker CD69 and co-stimulatory molecule CD86." (PMID 32849474, 2020). "CD86, a critical costimulatory molecule and ligand for CD28 and CTLA-4, is upregulated on monocytes and DCs upon virus infection in vitro and in vivo." (PMID 36752598, 2023). "This aligns with the fact that during viral infections, the secretion of IL-10 has been found to inhibit the expression of major histocompatibility class II (MHC II) and co-stimulatory molecules CD80 and CD86 on APCs." (PMID 35572964, 2022). "Overall, it is clear that viral infection modulates the phenotype of the novel DN3 subset such that these cells have reduced BAFFR and CD86 but elevated levels of FcRL5, CD22, and CD69 during severe disease." (PMID 36131937, 2022). "By contrast, CTLA4 is another ligand for CD80/CD86 which presents even a higher avidity than CD28, acting as a critical inhibitor of T-cell activation and proliferation in several viral infections." (PMID 36713151, 2022). "To determine how viral infection influenced the activation state of DN2 cells, we quantified levels of the CD69 and CD86 on this subset." (PMID 36131937, 2022). "To assess the influence of viral infection on DN1 B cell activation, we evaluated expression of the CD69 and CD86 activation receptors on virally infected and control individuals." (PMID 36131937, 2022). "Having correlated gene-specific viral integration with elevated PD-L1 and PD-L2 expression in HPV-positive HNSC, we next correlated any viral infection with PD-L1, PD-L2, PD-1, CD80, CD86, CTLA-4, Tim-3, LAG3, and 4-1BB expressions." (PMID 30911684, 2019). "In cells sorted three days after viral infection with Theiler's murine encephalomyelitis virus, surface receptors (including CD45, CD11b, CD40, CD80, CD86) were upregulated in spinal microglia compared to brain microglia." (PMID 24914808, 2014).
viral infection (continued). "At day 4 PI we observed that B cells (CD19+) from TLR3KO mice responded to viral infection by upregulating surface expression of the activation marker CD69 and the costimulatory molecule CD86 to levels comparable to that observed on B cells from WT NOD mice." (PMID 19122812, 2009). "Although both CD80 and CD86 provide costimulatory signals through CD28, it remains unclear whether they can fully compensate for each other’s functions during viral infections." (PMID 41280933, 2025). "Resveratrol has been shown to enhance antigen presentation of peritoneal macrophages via the upregulation of CD86, MHCII, and TLR4 levels, suggesting its role as a pseudorabies virus vaccine-adjuvant therapy, aiding in the host protection against viral infection." (PMID 38674902, 2024). "Since viral infections trigger interferon-induced gene expression in epithelial cells to orchestrate immune responses, we also stained for co-stimulatory molecules CD80 and CD86, or immune-activating molecules CEACAM5 and CEACAM6." (PMID 36827975, 2023). "In contrast, with severe viral infection, DN3 cells lose CD86 expression possibly indicating these cells may be less likely to receive T cell help." (PMID 36131937, 2022). "Exposure of adult AMs or neonatal AMs to RSV enhanced the expression of co-stimulatory molecules illustrated by the increase of CD86 median of fluorescence intensity (MFI) at the cell surface after 24 h of infection, thus demonstrating their ability to respond to viral infection." (PMID 33846534, 2021). "Higher expression of the suppressive marker PD-L1 and low expression of maturation markers CD86 and CD80 might be a result of viral infection." (PMID 33003471, 2020). "While previous studies suggest the overlapping function of CD80 and CD86 in antibody responses, during virus infection CD86 expression on B cells but not CD80 is critical for Tfh cell generation and function." (PMID 30158933, 2018). "Intriguingly, expression of CD86 was significantly downregulated on DN3 cells from subjects with mild or severe SARS-CoV-2 infection compared to healthy controls, suggesting DN3 cells may have less capacity to activate T cells with viral infection." (PMID 36131937, 2022). "At the chronic viral infection phase, KC showed no increased transcription of activation markers Cd80 and Cd86, but an increased expression of genes related to antigen presentation, whereas monocytes were more activated and expressed higher levels of Tnf transcripts." (PMID 27812182, 2016). "Importantly, since we used comparisons with cells infected with mut or empty vector in these assays, our approach ruled out the possibility that changes in MHC II, CD80 and CD86 were related to viral infection." (PMID 23251709, 2012). "Notably, the conditioned medium of MBT-2 cells either infected with Ad.shDCIR or Ad.LCY, or without viral infection could upregulate CD86 expression indicative of DC activation." (PMID 37892972, 2023). "RIG-I-/- BMDC infected with EMCV showed upregulation of the activation marker CD86 at levels similar to RIG-I+/+ BMDC, suggesting that RIG-I-/- BMDC do not have any defect in responding to viral infection via MDA5." (PMID 27438481, 2016).
colitis (35 papers, 2009 to 2025). Inflammation of the colon. "This study utilized CRC patient surgical samples, mouse models of colitis‐associated cancer, colonic organoid, and co‐culture cell line to examine the changes in CD11b/CD86 at different pathological region and detect the Wnt signaling pathway activity." (PMID 39302044, 2024). "Concordantly, our study revealed a marked reduction in CD86+ cell frequency in PBLs of ERAP1+/− colitis mice, which was further diminished after sulfasalazine treatment." (PMID 40977735, 2025). "In contrast, CD86+ cells were significantly reduced in ERAP1+/− colitis mice (p < 0.05); this reduction was also observed following sulfasalazine treatment (p < 0.05)." (PMID 40977735, 2025). "And the results also demonstrated that CD86 exhibited higher expression in mouse colitis lesions, whereas PDK2, CHDH, and ALDH5A1 displayed lower expression in these lesions." (PMID 38376420, 2024). "Ultimately, the verification of the expression of signature genes (ALDH5A1, CHDH, and PDK2) and their co-expression with M1 macrophages (CD86) was accomplished through the construction of inflammatory cell and colitis models." (PMID 38376420, 2024). "In colon tissue of colitis mice, there was an upregulation of pro‐inflammatory M1 type CD86+ macrophages, while a downregulation was observed in anti‐inflammatory M2 type CD206+ macrophages." (PMID 38790144, 2024). "The CD86 level was increased after inducing colitis, whereas PEG-CNPs injection prominently reduced that level." (PMID 37507801, 2023). "Western blotting revealed reduced expression of HMGCS2, ARG1, and CD206 and increased expression of iNOS and CD86 in colon tissues from the mouse models of DSS-induced colitis, further validating these findings." (PMID 38633005, 2023). "Results showed that Shikonin dose-dependently alleviated mice colitis, down-regulated expression of F4/80, iNOS and CD86, decreased IFN-γ, IL-1β, IL-6 and TNF-α, while increased IL-10 in mice colon." (PMID 36059938, 2022). "To explore the effect of triptolide on the polarization of macrophages in mouse colitis tissues, we used CD86 as the marker of M1 macrophage and CD206 as the marker of M2 to detect the infiltration of M1 and M2 macrophages in vivo by immunofluorescence." (PMID 33240279, 2020). "The percentage of MHC-II+CD86+ DCs was significantly higher in TNBS-induced colitis mice than in control mice." (PMID 32472435, 2020). "Specifically, colitis enhanced mRNA levels of CD86 (t7.8 = −3.2; p = 0.013) and TNF-α (t9.3 = −3.4; p = 0.006), did not change IL-1β expression, but decreased Nos2 expression (t7.092 = 5.237; p = 0.001)." (PMID 31882991, 2019). "However, a leukocyte population classified as CD11b+ CD11c- CD86+ was found to be significantly increased in DSS-colitis mice compared with healthy controls (p = 0.0019)." (PMID 40497975, 2025). "Moreover, the observation that a CD11b+ CD11c- population increased the expression of CD86+ in the DSS-colitis mice and was suppressed by the Fh15-treatment strongly suggests that Fh15 suppresses the activation of myeloid cells." (PMID 40497975, 2025). "Immunofluorescence staining of colon tissue revealed that DSS-induced colitis resulted in a pronounced upregulation of pro-inflammatory macrophage markers, specifically CD68 and CD86, which are associated with M1 macrophage polarization and heightened inflammatory responses." (PMID 40725052, 2025). "Furthermore, in an experimental model of colitis in mice, neutrophils isolated from lesions displayed an upregulation of CD86 alongside MHC II expression, suggesting a potential role in modulating inflammatory responses in the gastrointestinal tract." (PMID 40340446, 2025). "However, administration of QCHS (3, 6 and 12 g/kg) or SASP significantly downregulated the frequency of MHC-II+CD86+ DCs in the experimental colitis mice." (PMID 32967687, 2020).
colitis (continued). "Therefore, it is possible to speculate that Fh15 may suppress CD86-expressing leukocyte populations during the acute phase of colitis as a mechanism to prevent excessive T cell activation in the later stages of colitis." (PMID 40497975, 2025). "In contrast to acute and chronic DSS colitis, T cell-associated transcription factors or inflammatory cytokines were not altered, but we detected slightly increased mRNA levels of Il6, CD80, and Cd86 in PTPN2fl/flxCD11cCrexRAG−/− mice after naïve T cell transfer." (PMID 34201918, 2021). "Importantly, in the setting of IBD, CD80, but not CD86 blockade prevented CD4+ T cells with pathogenic potential to induce colitis in mice." (PMID 25505551, 2014). "Our immunofluorescence data showing decreased CD86+ and increased CD206+ macrophages align with emerging evidence that rebalancing macrophage phenotypes can ameliorate colitis." (PMID 40860883, 2025). "Based on these observations, we investigated the impact of Fn in a TNBS-induced murine colitis model and found that Fn markedly increased CD80+CD86+ DCs in the colonic LP and induced a Th17/Treg imbalance in MLNs." (PMID 41567217, 2025). "Immunofluorescence examination of sigmoid colonic tissues demonstrated that DSS-induced colitis significantly upregulated pro-inflammatory macrophage markers (CD68, CD86) while downregulating the anti-inflammatory marker CD163 relative to NC." (PMID 40725052, 2025). "In PPs, administration of the probiotic mixture to mice with colitis significantly decreased the frequencies of CD83+ (p < 0.05), CD86+ (p < 0.01), and CD11c+ cells (p < 0.01) compared to untreated colitis mice." (PMID 39201260, 2024). "The results demonstrated that HIF-MSC injection promoted a decrease in the relative expression ratio of F4/80+CD86+ and an increase in that relative expression ratio of F4/80+CD163+ in the colonic tissues of experimental colitis mice (p < 0.05)." (PMID 36979804, 2023). "As GPR84 was highly upregulated in macrophages and affected macrophage polarization in the LP of the colitis mice, we performed double immunofluorescence staining for GPR84 and CD86 in colonic mucosa sections from patients and healthy controls." (PMID 34912006, 2022). "The results showed that PF decreased mature DC counts in the TNBS-induced colitis model and reduced the percentage of MHC-II+CD86+ DCs and the expression of IL-12 in vitro and in vivo, which means that PF can inhibit DC maturation from imDCs." (PMID 32472435, 2020). "In contrast, AMD3100 blocked the therapeutic function of ERCs, and much more cells of CD11c+MHCII+, CD11c+CD86+, and CD11c+CD40+ DCs were found in colitis mice treated with AMD3100-pretreated ERCs, which were indistinguishable from that of the untreated group." (PMID 31286993, 2019). "Studies have reported that proinflammatory factors such as CD86 and IL-6 were elevated in IBD patients, and neutralization of IL-6 could relieve DSS-induced colitis." (PMID 38877444, 2024). "Our findings revealed that CD86 was not detectable in the control colon tissues, whereas its expression was increased in colitis tissues." (PMID 38376420, 2024). "PF inhibited MHC-II and CD86 expression on the DC surface (P < 0.05), decreased interleukin (IL)-12 secretion in vitro and in vivo (P < 0.05), and restored the TH17/Treg ratio in the mouse model of colitis (P < 0.05)." (PMID 32472435, 2020). "Additionally, QCHS reduced CD86 and MHC-II expression on DCs, decreased IL-12 production ex vivo and restored the Th17/Treg ratio in the colitis model." (PMID 32967687, 2020). "In the experimental colitis model, activated DCs produce numerous pro-inflammatory cytokines including TNF-α, IL-1β, IL-6, and IL-12 and express high levels of co-stimulatory molecules including CD80 and CD86." (PMID 31286993, 2019).